SNORD2 (small nucleolar RNA, C/D box 2)
Synonyms: R39B; snR39B
Gene: Small nucleolar RNA gene on chromosome 3 (186,784,796 to 186,784,864, forward strand). Ensembl gene ENSG00000238942.
Gene Ontology:
Biological process: RNA processing
Cellular component: nucleolus
Homologues: Orthologues: chimpanzee SNORD2 (100% identical), pig SNORD2 (100% identical), mouse Snord2 (99% identical), guinea pig SNORD2 (97% identical), rabbit SNORD2 (97% identical), rat Snord2 (96% identical).
Diseases named in the same sentence as SNORD2 in open-access papers:
SNORD2 is named in the same sentence as 3 diseases in open-access papers, as found by Europe PMC text mining. Sharing a sentence is not in itself a finding about the gene and the disease. The quoted sentences say what the papers report.
Parkinson disease (1 paper, 2020). A progressive degenerative disorder of the central nervous system characterized by loss of dopamine producing neurons in the substantia nigra and the presence of Lewy bodies in the substantia nigra and locus coeruleus. "Protein coding genes proximal to these snoRNAs were implicated in several neurologic conditions, including Wernicke‐Korsakoff Syndrome (Tex2/SNORD104), Spinocerebellar Ataxia (Nop56/SNORD57), and Parkinson Disease (EIF4A2/SNORD2)." (PMID 33135344, 2020).
SNORD2 also shares sentences with these, for which no sentence is quoted: cancer (1 paper); Spinocerebellar Ataxia (1).